SPP1 (secreted phosphoprotein 1)
Diseases named in the same sentence as SPP1 in open-access papers (continued):
Sharing a sentence is not in itself a finding about the gene and the disease.
nevus (2 papers, 2023 to 2025). Nevus (or naevus, plural nevi or naevi, from nævus, Latin for "birthmark") is the medical term for sharply circumscribed[1] and chronic lesions of the skin or mucosa. "Conversely, genetic ablation of Spp1 in nevus-bearing mice completely abolished the ectopic hair growth phenotype, confirming the necessity of OPN in this process." (PMID 40765999, 2025). "Therefore, the hair growth-activating effect of SPP1 in nevus skin requires epithelial CD44 signalling." (PMID 37344645, 2023).
non-Hodgkin lymphoma (2 papers, 2017 to 2021). Distinct from Hodgkin lymphoma both morphologically and biologically, non-Hodgkin lymphoma (NHL) is characterized by the absence of Reed-Sternberg cells, can occur at any age, and usually presents as a localized or generalized lymphadenopathy associated with fever and weight loss. "Similar to our findings in pediatric ALCL patients, circulating SPP1 was observed to be significantly higher in adult non-Hodgkin lymphoma patients compared to HDs." (PMID 33562105, 2021).
Peri-Implantitis (2 papers, 2021 to 2025). An inflammatory process with loss of supporting bone in the tissues surrounding functioning DENTAL IMPLANTS. "Finally, the potential target genes, namely, IL-6, TLR4, FN1, IL-1β, CXCL8, MMP-9, and SPP1, were found to be associated with peri-implantitis, and our results were consistent with those of previous studies." (PMID 34931168, 2021). "The intersecting genes, including IL6, TLR4, FN1, IL1β, CXCL8, MMP9, and SPP1, were revealed as potential genetic biomarkers and target genes of peri-implantitis." (PMID 34931168, 2021). "We found that IL-6, TLR4, FN1, IL-1β, CXCL8, MMP-9, and SPP1 might be used as potential biomarkers for the diagnosis of peri-implantitis." (PMID 34931168, 2021). "This study provides supportive evidence that IL6, TLR4, FN1, IL1β, CXCL8, MMP9, and SPP1 might be used as potential target biomarkers for peri-implantitis which may provide further therapeutic potentials for peri-implantitis." (PMID 34931168, 2021).
pneumoconiosis (2 papers, 2024 to 2025). An occupational lung disorder caused by inhalation of dust particles. "(iii) SPP1 in Pneumoconiosis: Pneumoconiosis encompasses a group of ILDs caused by occupational inhalation of inorganic dusts, such as coal, silica, and asbestos." (PMID 40559389, 2025). "SPP1 and ANXA1 is associated with pneumoconiosis and they may be the disease biomarkers." (PMID 39283905, 2024).
retinal diseases (2 papers, 2023 to 2025). "Another small cluster of proteins (cluster 4) that suggest the role of neurodegeneration in these retinal diseases are APP and related proteins (e.g., CYTC, CLSTN1, SPP1, APLP2)." (PMID 36875133, 2023).
transitional cell carcinoma (2 papers, 2022 to 2024). A malignant neoplasm arising from the transitional epithelium, usually affecting the urinary bladder, ureter, or renal pelvis. "SPP1 also proved to be markedly overexpressed in the bladder tissue and serum of transitional cell carcinoma patients and in MIBC patients compared to healthy individuals, which is consistent with our results." (PMID 35884419, 2022).
upper tract urothelial carcinoma (2 papers, 2022 to 2024). "High SPP1 expression levels were strongly connected with higher stage and grade in upper tract urothelial carcinoma." (PMID 38336764, 2024). "Results from another study found that SPP1 was upregulated in upper tract urothelial carcinoma cells and tissues, and high plasma SPP1 expression levels were strongly connected with higher stage and grade." (PMID 35884419, 2022).
uveitis (2 papers, 2017 to 2021). An inflammatory process affecting a part of or the entire uvea. "Interestingly, we have also previously found a significant downregulation of RMG-associated SPP1 expression in retinas of horses with uveitis." (PMID 34046254, 2021).
vascular neoplasm (2 papers, 2018 to 2023). A benign, intermediate, or malignant neoplasm arising from vascular tissue including arteries, veins, venous sinuses, lymphatic vessels, arterioles and capillaries. "Among these genes, Spp1 gene encoding osteopontin (OPN) was represented in both PI3K/Akt signaling and ECM-receptor interaction pathways, suggesting its potentially prominent roles in mediating phenotypic effects of autophagy blockade in vascular tumor cells." (PMID 36813768, 2023).
Vestibular schwannoma (2 papers, 2013 to 2025). A vestibular schwannoma (also known as acoustic neuroma, acoustic neurinoma, or acoustic neurilemoma) is a benign, usually slow-growing tumor that develops from the VIIIth cranial nerve supplying the inner ear. "Our research demonstrated that the SPP1/CD44 pathway was activated in vestibular schwannoma tissues, aligning with findings from earlier studies." (PMID 40629113, 2025). "Our findings also demonstrate that the MET signaling pathway, which is possibly enhanced by the upstream signaling of SPP1, ITGA4/B6, PLEXNB3/SEMA5A and CAV1, appears to play a paramount role in the development and maintenance of vestibular schwannoma." (PMID 23354516, 2013).
acute pancreatitis (1 paper, 2024). An acute inflammatory process that leads to necrosis of the pancreatic parenchyma. "Focusing on the gene Spp1, we found 25.7% of spots positive for EMT-like SVG expression in Ehmt2+/+ mice with acute pancreatitis, which notably increased to 45.7% in Ehmt2fl/fl pancreas." (PMID 38948355, 2024).
adenocarcinoma in situ (1 paper, 2020). A lesion in which the normally situated glands are partially or completely replaced by atypical cells with malignant characteristics. "Alternatively, in the six tumours lacking micro invasion, categorised as a subtype of adenocarcinoma in situ (blue numbers), a range of OCT4 and SPP1 gene scores were observed." (PMID 32503462, 2020).
adhesive capsulitis (1 paper, 2025). "Interestingly, in adhesive capsulitis (frozen shoulder), SPP1 is downregulated compared to non‐inflamed tissue, despite no significant changes in macrophage abundance, suggesting that the nature and chronicity of inflammation strongly influence the emergence and function of SPP1+ macrophages." (PMID 40395129, 2025).
amoebiasis (1 paper, 2022). "The prime module in protein-protein interaction network of DEGs, including ADAMTS2, COL10A1, COL1A1, COL1A2, COL8A1, BGN, and SPP1, was enriched in protein digestion and absorption, ECM-receptor interaction, focal adhesion, PI3K-Akt signaling pathway, and amoebiasis." (PMID 35726219, 2022). "In detail, COL1A2, COL1A1, and COL10A1 were enriched in protein digestion and absorption; COL1A2, COL1A1, and SPP1 were enriched in ECM-receptor interaction, focal adhesion, and PI3K-Akt signaling pathway; COL1A2 and COL1A1 were further enriched in amoebiasis (P < 0.05)." (PMID 35726219, 2022).
aneurysmal disease (1 paper, 2023). "Previous studies have also implicated SPP1 in both abdominal and thoracic aneurysmal disease by upregulating matrix proteinases via NF-κB, thereby accelerating tissue degeneration." (PMID 37698712, 2023).
Arrhythmia (1 paper, 2025). Any cardiac rhythm other than the normal sinus rhythm. "Several of our identified r.m. genes may establish a genetic susceptibility for enhanced SPP1+ macrophage recruitment and activation—a cellular mechanism previously observed in arrhythmias but whose genetic basis remained unclear." (PMID 40900730, 2025). "Another key question in arrhythmia pathogenesis is what genetic mechanisms drive the recruitment and activation of SPP1+ macrophages." (PMID 40900730, 2025). "Beyond arrhythmia, accumulating evidence highlights SPP1+ macrophages as central mediators across diverse cardiac pathologies." (PMID 40900730, 2025). "These genomic insights were integrated with single-cell data (7 arrhythmias, 5 controls) to examine cell-type-specific gene expression changes, with particular focus on SPP1+ macrophage states." (PMID 40900730, 2025). "This suggests a potential mechanism through which SPP1+ macrophages may directly mediate inflammatory-fibrogenic network, two critical hallmarks in arrhythmia progression and persistence." (PMID 40900730, 2025).
arterial disease (1 paper, 2021). "It would be interesting to examine whether those secreted proteins (Bgn,Cpe,Emillin1,Fstl1,Nid1,Mgp,Sparc, and Spp1) validated by our ISH are the result of the arterial disease or play a direct causative role." (PMID 34762601, 2021).
cardiac sarcoma (1 paper, 2024). "Our research also highlights a unique TME in cardiac sarcoma, marked by an increase in myeloid‐derived suppressor cells, specifically SPP1+ and OLR1+ macrophages, which are implicated in advanced tumour progression." (PMID 39658531, 2024).
cervical (1 paper, 2021). "We found that C1QC+ and SPP1+ TAMs gene signatures were more suitable to divide cervical patients into subgroups with distinct clinical outcomes than M1/M2 gene signatures." (PMID 34295336, 2021). "In conclusion, C1QC+ and SPP1+ TAMs gene signatures derived from TAMs can divide cervical patients into subgroups with different prognosis and tumor stage, which may due to different immune cell infiltration." (PMID 34295336, 2021).
cholesteatoma (1 paper, 2012). A pathologic process characterized by the proliferation of keratinizing squamous epithelium resulting in the accumulation of keratin and cells in the middle ear and/or mastoid. "Among the 811 up-regulated extramatrix protein genes, MMP1, MMP7, MMp9, MMP10 and MMP12 and their substrate Osteopontin (SPP1) were amplified and their expression was significantly higher in cholesteatoma than in external canal skin (logFC>10)." (PMID 23285167, 2012). "SPP1 (Osteopontin) serves as a substrate for MMPs and thrombin, it can bind to extracellular matrix proteins (fibronectin and collagen), and is also up-regulated in cholesteatoma (logFC 280 compared to canal skin)." (PMID 23285167, 2012). "Genes which were important for inflammation are for example KRT 6 B, SPP1, and S100A7A are highly up-regulated in cholesteatoma compared to external auditory skin." (PMID 23285167, 2012). "Real-time PCR of PI3, SPRR1B, LCN2 (lipocalin 2), MMP1, MMP9, MMP10, MMP12, SPP1, GJB2, Bcl-xl (BCL2L1), cIAP2 (BIRC3), S100A7A (koebnerisin), S100A9, SERPINB3, CEACAM6, KRT6B and SERPINB4 revealed that the expression levels of these proteins were higher in cholesteatoma than in external canal skin." (PMID 23285167, 2012).
choroidal neovascularization (1 paper, 2022). An eye disorder described by the growth of new blood vessels that originate from the choroid through a break in the Bruch membrane into the sub–retinal pigment epithelium (sub-RPE) or subretinal space. "In the eye, SPP1 expressed by retinal microglia was recently identified as a key mediator of retinal inflammation in the mouse model of choroidal neovascularization (CNV) and detected in human CNV." (PMID 35371110, 2022).
Coccidioides infection (1 paper, 2025). "In response to Coccidioides infection, Spp1+ macrophages express high levels of pro-inflammatory (Nos2, Tgfb1, Il1β, and Il6) and fibrotic/wound healing associated genes (Inhba, Spp1, Arg1, Pdgfb, and Fn1)." (PMID 40704794, 2025). "Future studies are needed to clarify how PD-L1+ neutrophils shape outcomes during Coccidioides infection and to determine if PD-L1+ neutrophils arise through fungal contact-dependent mechanisms, similar to Spp1+ macrophage differentiation." (PMID 40704794, 2025). "Trajectory analysis indicated classical monocytes transition into Spp1+ macrophages following Coccidioides infection, and in vitro experiments indicated that this differentiation is dependent on fungal contact." (PMID 40704794, 2025). "Our analysis of the early immune response to Coccidioides infection demonstrated rapid influx and activation of neutrophils, particularly PD-L1-expressing subsets, and the differentiation of monocytes into Spp1+ macrophages." (PMID 40704794, 2025). "Additional studies are needed to clarify the role of Spp1+ macrophages in disease outcomes; however, Spp1+ macrophages also develop in response to virulent Coccidioides infection, expanding from 5 to 14 days post infection (dpi) and demonstrating a similar fibrotic phenotype." (PMID 40704794, 2025).
congenital nevus (1 paper, 2023). "By using Tyr-NrasQ61K; Spp1−/−mice, researchers found that SPP1 loss-of-function mutations are sufficient to reverse the static hair cycle in the skin of congenital nevus and that SPP1 can induce new hair growth." (PMID 38136855, 2023).
deep venous thrombosis (1 paper, 2022). "Among others, downstream analyses revealed colocalization of the OPN association signal at SPP1 with expression in pancreas tissue, and at KLKB1 with various plasma proteins in trans, and with phenotypes (bone disorder, deep venous thrombosis) in human tissue." (PMID 35385482, 2022).
diabetic macular edema (1 paper, 2021). "We speculate that a decrease in SPP1 expression level might contribute to RMG swelling in diabetic macular edema." (PMID 34046254, 2021).
Duodenal polyposis (1 paper, 2019). Presence of multiple polyps in the duodenum. "DEGs with therapeutic potential include SPP1, which is involved in both cyclooxygenase and epidermal growth factor receptor pathways targeted by the sulindac/erlotinib combination for duodenal polyposis." (PMID 31211760, 2019).
gallbladder carcinoma (1 paper, 2025). "Accordingly, high expression of ASPH can activate the four pathways of FN1 signaling pathway, COLLAGEN signaling pathway, VISFATIN signaling pathway and SPP1 signaling pathway, these pathways occur mainly in the epithelial, myeloid cell, myeloid cell and macrophage of gallbladder carcinoma." (PMID 40110547, 2025).
hearing loss (1 paper, 2024). "Although differentially expressed genes associated with hormone transport are expressed in SGNs, including Slc7a5 and Syt7 as well as Spp1, their link to hidden hearing loss is less clear." (PMID 39049179, 2024).
HIV-1 infection (1 paper, 2021). The type species of lentivirus and the etiologic agent of acquired immunodeficiency syndrome (AIDS). "We also found that knockdown of SPP1 increased the susceptibility of T cells to HIV-1 infection." (PMID 33504604, 2021). "Altogether, our findings shed light on the role of SPP1 in HIV infection, but further investigation is required to fully elucidate the role of SPP1 in HIV-1 infection." (PMID 33504604, 2021). "In contrast, a previous study showed that SPP1 promotes HIV-1 infection in human-derived macrophages through the downregulation of IκBα and subsequent activation of NF-κB." (PMID 33504604, 2021). "Therefore, SPP1 may indirectly prevent HIV-1 infection through these cytokine signals." (PMID 33504604, 2021). "Even though latently infected cells showed a very similar transcriptomic profile to that of non-infected cells, we found that SPP1 and APOE were significantly enriched in non-infected cells compared to that in latently infected cells and that knock down of these genes promoted HIV-1 infection." (PMID 33504604, 2021).
Hyperkalemia (1 paper, 2020). An abnormally increased potassium concentration in the blood. "In addition, mega-analysis discovered one hyperkalemia-specific promoter, SPP1, also presented significantly increased expression in the case of LSCC (p = 2.81e-6; LFC = 2.64)." (PMID 33092550, 2020). "In addition, meta-analysis identified one hyperkalemia promoter, SPP1, as a novel contributor for LSCC (LFC = 2.64; p-value = 2.81e-6)." (PMID 33092550, 2020). "Genes associated with hyperkalemia may also play roles for the development of LSCC, and SPP1 could be a promoter for both hyperkalemia and LSCC." (PMID 33092550, 2020).
hyperostosis (1 paper, 2014). Excessive thickening of bone. "Conversely, Spp1 has been reported to be upregulated in spinal hyperostosis of twy mice, which represent another Enpp1 allele." (PMID 24906371, 2014).
hyperplasia (1 paper, 2023). An abnormal increase in the number of cells in an organ or a tissue with consequent enlargement. "Additionally, a genetic model of prostate hyperplasia derived from Nfib-knockout mice, which manifests epithelial and stromal hyperplasia alongside augmented collagen deposition, also presents elevated Spp1 expression; however, the identity of cells producing OPN was not revealed in this study." (PMID 38001899, 2023).
inclusion body myositis (1 paper, 2025). A slowly progressive degenerative inflammatory disorder of skeletal muscles characterized by late onset weakness of specific muscles and distinctive histopathological features. "One study identified six macrophage subpopulations, including Spp1‐ and Lgals3‐expressing subtypes in dystrophic regions of DMD mice, with human analogs detected in biopsies from patients with DMD, inclusion body myositis (IBM), and other inflammatory myopathies." (PMID 41431371, 2025).
laryngeal diseases (1 paper, 2021). "However, reports of SPP1 in laryngeal diseases, especially LSCC, are insufficient." (PMID 33954053, 2021).
low grade glioma (1 paper, 2024). A grade I or grade II glioma arising from the central nervous system. "Furthermore, when comparing chromatin accessibility analysis between GBM and low-grade glioma (LGG), it was discovered that the SPP1 promoter region contains two GBM-specific motifs, which are consistent with the binding sites of CEBPB in other cell types." (PMID 38994023, 2024).
lung neoplasm (1 paper, 2011). A benign or malignant, primary or metastatic neoplasm involving the lungs. "Overall from previous and current tumor analyses using different dosing regimens, carcinogens, and strains of mice, a panel of common transcripts (e.g. Arg1, Areg, Ereg, Ccr2, Cdkn1a, Gja1, Ptgis, Spp1) may provide a useful tool for early diagnosis of lung neoplasm." (PMID 22039513, 2011).
MALT lymphoma (1 paper, 2020). An indolent, extranodal type of non-Hodgkin lymphoma composed of small B-lymphocytes (centrocyte-like cells). "Furthermore, MMP12 and SPP1 should be analyzed in larger samples of IgG4-ROD and other IgG4-RDs, and it is also necessary to examine the dynamics of these genes and proteins in IgG4-positive MALT lymphoma." (PMID 33121169, 2020).
myelofibrosis (1 paper, 2023). A partial or complete replacement of the bone marrow stroma by fibrous tissue. "We focused on SPP1, the gene coding for osteopontin (OPN), and showed that SPP1 is a transcriptional target of MAF and that the overproduction of OPN at least partially contributes to the increased fibroblast proliferation and collagen production that underlies the development of myelofibrosis." (PMID 36928007, 2023).
Niemann-Pick disease type C (1 paper, 2026). NPC is a complex lipid storage disease mainly characterized by the accumulation of unesterified cholesterol in the late endosomal/lysosomal compartment. "Experimental validation in primary microglia isolated from a mouse model of Niemann-Pick disease type C, also known as juvenile Alzheimer's disease, supports the conservation of key components of this program and highlights Spp1 as a biomarker of disease-associated microglia states." (PMID 42011986, 2026).
Optic neuropathy (1 paper, 2023). "Molecules, such as SPP1, may serve as biomarkers for early diagnosis or be exploited to prevent vision loss in glaucomatous optic neuropathy." (PMID 37624696, 2023).
Oral leukoplakia (1 paper, 2024). A thickened white patch on the oral mucosa that cannot be rubbed off. "Furthermore, SPP1 shows a strong association with oral leukoplakia driven by HNSCC, highlighting its potential as a diagnostic and prognostic biomarker, as well as a promising therapeutic target for HNSCC." (PMID 39596132, 2024).
orbital disease (1 paper, 2024). "In addition, as compared to IgG4 related orbital disease, there was significant up-regulation of some of the genes observed, including matrix metallopeptidase 12 (MMP12) and secreted phosphoprotein 1 (SPP1)." (PMID 38322414, 2024).